CRP (C-reactive protein)
Diseases named in the same sentence as CRP in open-access papers (continued):
Sharing a sentence is not in itself a finding about the gene and the disease.
infection (continued). "For CRP the best cut-off value for infections detection was 5.3 mg/dL with a sensitivity of 54.9%, specificity of 69.6% (AUROC 0.648, CI 95%: 0.560–0.735, p < 0.002, Yourden index J = 0.458)." (PMID 36143057, 2022). "Similar to previous studies, evidence of infection or inflammation including elevated concentrations of C-reactive protein, procalcitonin, ferritin, and d-dimers was reported." (PMID 35428202, 2022). "In our study, we cannot dismiss the different clinical scenarios displayed by our patients, including the duration of infection, symptomatology, and CRP (C-reactive protein) levels." (PMID 35265721, 2022). "Concerning the performance of nCD64 index in predicting the 28-day hospital mortality among patients with infection, the AUC (0.7582), at the cut-off value of 13.50, was higher than that of CRP (0.7121), but lower than that of PCT (0.7834)." (PMID 35967346, 2022). "Elevated C-reactive protein (CRP) levels, indicating inflammation, infection, or progress of cancer, have also been associated with decreased appetite." (PMID 35629338, 2022). "Considering inflammatory/infection indices at day 1, median procalcitonin was 0.37 (0.19–1.29) ng/mL, median CRP was 19 (5.6–31) mg/L; white blood cells count 8070 (6263–11,000)." (PMID 35276795, 2022). "Surgical stress, postoperative infection and tissue injury can increase the level of serum C-reactive protein." (PMID 36371192, 2022). "In our study serious infections tended to have higher CRP values, however serious infections with CRP < 5 mg/L were also found." (PMID 36333682, 2022). "CRP, an acute-phase protein, is one of the most commonly used biomarkers to demonstrate infection and inflammation." (PMID 36404511, 2022). "High CRP levels reflect severe tissue injury and infection which lead to remarkable hypoproteinemia." (PMID 35109818, 2022). "A significant body of evidence suggests the WBC count and CRP levels in the blood serum as the markers with the greatest accuracy in distinguishing infection from non-infection." (PMID 35585489, 2022). "Among those with reported fever, 60% had infection, while among those with vomiting, 63% had infection as measured by CRP and AGP levels." (PMID 36211493, 2022). "An increased A→G mutation frequency was associated with low viral load and tended to increase during the course of infection in patients with severe disease and also increased with the degree of inflammation, as reflected by levels of CRP in blood." (PMID 35064076, 2022). "Previous studies on host biomarkers for IPA investigated mainly genetic markers (single-nucleotide polymorphisms, SNPs), cytokines, and already established infection and inflammation markers such as CRP." (PMID 35205926, 2022). "C-reactive protein is an acute protein mainly produced by hepatocytes that increase dramatically in response to injury, infection, and inflammation, which plasma level can reflect the severity of inflammation." (PMID 36225581, 2022). "Laboratory markers, including white blood cell (WBC) count, polymorphonuclear leukocyte (PMN) count, erythrocyte sedimentation rate (ESR), and C-reactive protein(CRP) level, have been used for the diagnostic investigation of foot and ankle infections." (PMID 35926065, 2022). "In a population, a combination of AGP and CRP is useful in monitoring infection not only in symptomatic individuals but also in monitoring infection in asymptomatic or healthy individuals." (PMID 36211493, 2022). "The use of conventional biomarkers (i.e., leukocyte and neutrophil counts, CRP) has shown limited predictive ability with low specificity for the diagnosis of infection." (PMID 35346082, 2022). "A total of 15 patients had plateauing/ incline in CRP levels on or after the third post-operative day, these patients had presented with clinical signs of infections such as local hyperthermia, fever, skin necrosis, and discharge from the surgical site." (PMID 35350520, 2022).
infection (continued). "C-reactive protein (CRP) or procalcitonin (PCT) alone has limitations in the early detection of infection or inflammation due to shortcomings in specificity and varied cut-off values." (PMID 36555941, 2022). "CRP is an acute-phase inflammatory protein that is a significant surrogate marker for inflammation or infection." (PMID 35473805, 2022). "Research has suggested that CRP is an acute inflammatory reactant whose levels increase in response to IL-6-mediated purulent infections, such as active TB." (PMID 36296203, 2022). "Although seeming to have average sensitivity and specificity, the increase in CRP levels is slow during the first 24-48 hours of infection, which negatively affects its sensitivity." (PMID 36158418, 2022). "CRP is present in minute quantities in healthy persons, increases quickly with infection within a few hours, and then rapidly decreases when the inflammation subsides." (PMID 36676644, 2022). "Studies have also suggested that IG% is a more predictive marker in the early diagnosis of any infection as compared to procalcitonin and CRP values, which are well-known markers that have been previously studied." (PMID 36295620, 2022). "In particular, IL-6 is a more sensitive predictor of bacterial infection compared to PCT and CRP, and different levels of IL-6 predict different extents of infection." (PMID 35463642, 2022). "Numerous animal studies have shown the essential role of CRP in infections and inflammatory processes." (PMID 35620114, 2022). "Diagnosing bacterial infection in patients with febrile neutropenia is typically based on standard infection markers such as CRP and PCT." (PMID 36670590, 2022). "CRP is an acute inflammatory protein produced by the liver and significantly increases when there is inflammation or infection in your body." (PMID 35873709, 2022). "On average, CRP levels were controlled 9.5 days after infection and all patients who developed infections were discharged after the infection was controlled." (PMID 36484930, 2022). "CRP is an acute phase protein, routinely utilized as a biomarker of infection, inflammatory processes and cardiovascular events." (PMID 36555850, 2022). "C-reactive protein (CRP), an acute phase reactant has been suggested as a superior marker to predict potential infection in fracture surgery." (PMID 35991254, 2022). "Although low specificity has been noted as a limitation of using CRP levels for diagnosis of orthopedic infections, our study’s specificity was high, perhaps because we only included severely destructive infection cases." (PMID 35246574, 2022). "There is growing evidence that CRP serves an important function in the inflammatory process as well as in hose response to infection, including the complement pathway, apoptosis, phagocytosis and cytokine production." (PMID 35514333, 2022). "C-reactive protein (CRP) is a homomeric membrane protein that can be irreversibly dissociated into five separate monomers at sites of inflammation and infection." (PMID 35514333, 2022). "We found that infection indexes, such as WBC count, ESR, and CRP level, were independent risk factors for SSI; further analyzed by ROC curves, their best cutoff values were 6.69 × 109/L, 39.45 mm/1 h, and 18.79 mg/L, respectively." (PMID 35813227, 2022). "It acts on early host response to infection, precedes increases in CRP, and is observed after tumor necrosis factor alpha (TNFα) has been released." (PMID 34846061, 2022). "The odds of having infection, based on increased CRP and AGP, in underweight infants was 3.7 times higher (OR: 3.7; 95% CI: 2.3, 4.5; P = 0.019)." (PMID 36211493, 2022). "C-reactive protein (CRP) is a protein that rises sharply in response to infection or tissue damage in the body." (PMID 35967416, 2022). "Commonly used clinical infection markers, such as PCT and CRP, have certain limitations in the diagnosis of infection." (PMID 35432366, 2022).
infection (continued). "PCT and NGAL are always combined with CRP in clinical settings to predict and diagnose infection levels." (PMID 35692686, 2022). "As a result, monitoring of CRP is advised in order to assess the trajectory of the infection in children." (PMID 36497665, 2022). "Using serum C-reactive protein (CRP) data from 461 052 UK Biobank participants, we defined incidence rate ratios (IRRs) for death from infection, cardiovascular disease, or other causes and adjusted for comorbidities and the use of anti-inflammatory therapies." (PMID 35535512, 2022). "The C-reactive protein (CRP) is an acute phase protein produced in the liver and is utilized as a marker of infection and inflammatory processes." (PMID 35572999, 2022). "Thereby, a significant increase of CRP on phagocytic activity and opsonization demonstrated macrophage activation in the early stage of infection." (PMID 35402541, 2022). "Previously, CRP shows low specificity and limited correlation with the disease activity in comparison to other infection indexes." (PMID 36292098, 2022). "Procalcitonin is more specific than C-reactive protein in the diagnosis of infection (37th most cited article) and is related to the severity of organ failure and mortality in children with septic shock (32nd most cited)." (PMID 35223703, 2022). "OOH clinicians have reported a desire for more access to POC testing, including CRP testing to look for infections." (PMID 35892398, 2022). "If the CRP value is higher than 29.15 mg/dL, it is better to continue IV antibiotics or consider debridement for better infection control." (PMID 35626186, 2022). "CRP is an important indicator of inflammation and its synthesis rises rapidly as a response to inflammatory stimuli and is an early sensitivity to infection." (PMID 35845744, 2022). "sTREM-1, a circulating marker of the host immune response to infection, was more strongly associated with mortality than common clinical markers, lactate, PCT, and CRP." (PMID 35830474, 2022). "Inflammation (elevated in CRP levels) which was related to infection or injury led to a reduction in deiodinase activity." (PMID 35996695, 2022). "In addition, CRP and IL-6 might directly accelerate protein degradation and indirectly influence important metabolic pathways to make patients frail, thereby causing patients to progress rapidly to severe or critical infection or even death." (PMID 35037900, 2022). "It is known that during infection with B. canis, the acute-phase response is triggered, as evidenced by the increased fibrinogen, C-reactive protein, and serum amyloid A concentration in the blood." (PMID 35163517, 2022). "The changes in serum SAA, PCT and CRP in the infection group before and after treatment were compared." (PMID 35775463, 2022). "CRP is an acute inflammatory protein that increases up to 1,000-fold at sites of infection or inflammation." (PMID 35309171, 2022). "Noteworthy is that CRP is also in the inflammatory process by activation of the classical complement leading to the protection against infection." (PMID 36018845, 2022). "Lactate is one of several non‐specific ‘infection’ markers used in current clinical practice, the most common of which is CRP." (PMID 35866444, 2022). "CRP, a member of the pentraxin family of proteins, consists of five 23 kDa subunits that can be increased 1,000-fold or more during infection, inflammation and tissue damage." (PMID 36589832, 2022). "C-reactive protein is an acute inflammatory protein that rises at sites of inflammation or infection, accelerating phagocytic reactions, chemotaxis and platelet activation and increasing cell-mediated immunity." (PMID 35106154, 2022). "C-reactive protein is an acute-phase protein that increases significantly in response to inflammation and infection, especially bacterial infections." (PMID 35476639, 2022).
infection (continued). "As previously reported, testing with a serum CRP cut-off value of 10 mg/L was a useful and simple screening method for infection even with RHD14,23." (PMID 35246574, 2022). "There was a statistically significant association between the modified Glasgow prognostic scoring system (mGPS), C-reactive protein-to-albumin ratio (CAR), neutrophil–platelet score (NPS) and risk of developing a surgical site infection (all p < 0.05)." (PMID 34628535, 2022). "Increments in systolic blood pressure and decrements in heart rate, temperature, total NEWS score, and CRP were typical occurrences during the hospital stay for patients acutely admitted with serious infections." (PMID 35406374, 2022). "Seasonality also had an impact on innate immune parameters, including leukocytes and C-reactive protein, resulting in possible inflammation or infection." (PMID 35514333, 2022). "The multivariate logistic regression analysis revealed significant associations of CRP, HGB, neutrophil, PLT, and WBC levels, and NLR with infections (p < 0.05 for all)." (PMID 36095013, 2022). "There was a significant relationship between sTREM-1 and PCT (p = 0.001), and CRP values (p = 0.02) in diagnosis of IA and all of these biomarkers elevated during infection." (PMID 35752831, 2022). "For infection patients, there was a significant increase in systolic blood pressure, and significant decreases in heart rate, temperature, total NEWS score, and CRP during the hospital stay compared to the non-infection group." (PMID 35406374, 2022). "Currently available inflammatory biomarkers, such as leukocyte count, CRP, and procalcitonin, reflect the host inflammatory response to infection." (PMID 35582505, 2022). "CRP is an inflammatory marker primarily synthesized in liver hepatocytes and traditionally utilized as a marker of infection, inflammation, and cardiovascular events." (PMID 35251855, 2022). "Responding to infection or tissue inflammation, the production of CRP is rapidly stimulated by cytokines, particularly interleukin (IL)-6." (PMID 36294849, 2022). "The extensive use of CRP testing in Norwegian primary care, especially in consultations with patients with suspected infection and in OOH services, is described in previous studies from Norway." (PMID 34263906, 2022). "As CRP is usually markedly elevated only in acute inflammation or infection, high-sensitivity CRP (hsCRP) measurement is useful in low-grade and chronic conditions, as it allows accurate measurement at low levels." (PMID 35832286, 2022). "ESR and CRP levels are elevated in various conditions, including inflammations, infections, and malignancies." (PMID 35144674, 2022). "Interestingly, after excluding individuals with follow-up hs-CRP levels exceeding thresholds that may indicate an intercurrent infection or high-risk cardiovascular inflammation, the study sample consisted of older adults likely at average or lower risk of diseases (e.g., cardiovascular diseases)." (PMID 36494677, 2022). "Physiologically, CRP is synthesized in the liver in response to stimulation of IL-6 increased by inflammation including infection." (PMID 36555941, 2022). "C-reactive protein (CRP) is an acute-phase protein that is synthesized by the liver due to infection and is an important component of the immune system." (PMID 36551142, 2022). "CRP is known to be an acute phase reactant found at higher levels during the early stages of injury, infection, or other inflammatory stimuli." (PMID 35978214, 2022). "The CRP/PCT ratio was suitable for discriminating between infection-related and cancer-related fever." (PMID 36614896, 2022). "Some patients presented elevated laboratory parameters related to infection, such as ESR, CRP, and WBC, confirming their important role in the diagnostic process of these infections." (PMID 35628858, 2022).
infection (continued). "This study aims at assessing CRP level in post-operative orthopaedic trauma patients and determining the reliability of CRP as an early indicator of postoperative infection." (PMID 35350520, 2022). "C-reactive protein shows high expression during inflammatory conditions such as rheumatoid arthritis, some cardiovascular diseases, and infection." (PMID 36428884, 2022). "There is no general laboratory data such as complete blood count, liver function test, and infection markers such as C-reactive protein, which is also the limitation of our study." (PMID 35571125, 2022). "Among all 201 children, the infection group had greater levels of CRP, nCD64 index, and PCT (all p < 0.05)." (PMID 36522701, 2022). "CRP is an acute-phase reactant that rises in the bloodstream in response to infection or tissue damage." (PMID 35978027, 2022). "CRP levels greater than 10 mg/L (clinical levels) are likely to indicate current infection and acute inflammation." (PMID 36411323, 2022). "CRP is commonly used to identify and monitor the progression of inflammatory processes due to infection." (PMID 35178206, 2022). "Our data suggest that NP is produced at the early phase of infection by different signaling pathways and/or cells from those of CRP and IL-6." (PMID 35529699, 2022). "CRP is an acute-phase reactant that is released in response to infection, tissue injury, and inflammation and is mediated by cytokines, such as interleukin-6, and -1." (PMID 35463642, 2022). "Other factors, such as the influence of infection (C-reactive protein levels ([CRP]), weight, mechanical ventilation (FiO2), and amount of enteral nutrition, showed no such association (P > 0.05)." (PMID 35473303, 2022). "Incision infection after calcaneal fracture affects the clinical treatment effect, and serum IL-2, IL-6, and CRP levels increase in patients with postoperative incision infection after bone fracture." (PMID 36091601, 2022). "Increases in preoperative C-reactive protein will lead to increases in the probability of postoperative infection, and infections after joint replacement can be catastrophic." (PMID 35831810, 2022). "Since there are presently no recognized and accepted biomarkers for assessing SCI levels alone, SCI is usually measured by combining the clinical biomarkers of acute inflammation and infection, such as CRP, IL-6, and TNF-α." (PMID 36556207, 2022). "In a meta-analysis, consisting of a total of nine studies, diagnostic accuracy of SAA in EOS and LOS (measured 8–96 h after onset of infection) was found to be moderate and comparable to those of CRP and PCT." (PMID 35345614, 2022). "According to ROC curve analysis, age (AUC = 0.681), biological sex (AUC = 0.620), BMI (AUC = 0.706), dosage group (AUC = 0.636), WBC count (AUC = 0.626), and CRP (AUC = 0.608) were all predictive of infection." (PMID 35979059, 2022). "CRP is synthesized by the liver in response to infection, inflammation, and tissue damage, and is regulated by several cytokines." (PMID 35464000, 2022). "Reflecting a more complex and severe infection, serum markers for systemic inflammation and infection, including CRP and WBC in peripheral blood, were the highest in DR(+) patients." (PMID 36050427, 2022). "We and others have found that a CRP increase 1–3 days after the onset of symptoms has a high specificity for infections in neonates." (PMID 36233706, 2022). "Blood infection parameters were relatively high, with CRP levels 173 ± 15.8 mg/L in the surgical decompression group and 150.3 ± 14.6 mg/L in the instrumentation group (p < 0.005)." (PMID 35536406, 2022). "There was some literature suggesting that IL-6 rises earlier than PCT and CRP after the onset of infection, which also correlates with the severity of the infection." (PMID 35794529, 2022). "Inflammatory markers (white blood cell count, neutrophil count, and level of C reactive protein) are important indicators of inflammation that can be used to evaluate infection." (PMID 35768446, 2022).